IL22 (interleukin 22)
Diseases named in the same sentence as IL22 in open-access papers (continued):
Sharing a sentence is not in itself a finding about the gene and the disease.
dermatitis (continued). "The inhibition of the LAT1 amino acid transporter effectively blocks IL-17 and IL-22 secretion by Th17 and γδ T cells, thus preventing imiquimod (IMQ) and IL-23-induced skin inflammation." (PMID 34831399, 2021). "In the murine dermatitis model, topically applied FICZ significantly increased FLG expression, improved dermatitis clinical scores and TEWL and inhibited AD-like skin inflammation with a decrease of IL-22 expression." (PMID 34198894, 2021). "Six hours after the last application of FAg, mRNA expression of IFN-γ increased by 163-fold in the AD-like dermatitis as compared with that in control mouse skin, and the expression of TNF-α, IL-12/IL-23, IL-17, and IL-22 also increased." (PMID 30838224, 2019). "The promotion of IL-17A and IL-22 production induced by M. globosa may restrain the development of TSLP and inhibit the Th1/Th2 type skin inflammation." (PMID 40309262, 2025). "HFD reduced mRNA levels of IL-17A, IL-17F, IL-22, IL-1β, tumor necrosis factor (TNF)-α, CXCL1, CXCL2, and keratin 16 and increased those of transforming growth factor (TGF)-β1 and cyclin-dependent kinase inhibitor 1A in imiquimod-induced dermatitis." (PMID 37762500, 2023). "All mice with oxazolone-induced dermatitis had a dramatic increase in IL-1β, IL-4, IL-6, IL-10, TNF-α, IFN-γ, IL-16, IL-17C, IL-17E, IL-17F, IL-21, IL-22, and MIP-3a, whereas the concentrations of IL-12p70, IL-2, IL-17A, and IL-23 were lower in dermatitis mice." (PMID 37889696, 2023). "The effect of IL-6 on the IL-22-IL-22Rα system in the context of the skin inflammation is, however, not well documented." (PMID 31781680, 2019). "Similarly, IL-22, while relevant to skin inflammation, was not evaluated in vivo due to the prioritization of cytokines more commonly associated with the IMQ-induced murine model, such as IL-17 and IL-23." (PMID 40667480, 2025). "The pathogenesis of dermatitis involves epidermal barriers abnormalities, leading to heterogeneous immunological dysregulations predominantly in type 2 immunity (Th2, IL-4, IL-13, IL-31), but also including varying degrees of upregulation of the Th1 (IFN-γ), Th17 (IL-17), and Th22 axes (IL-22)." (PMID 38550585, 2024). "Similarly, knockout of IL‐17A or IL‐22 on the Flgft/ft background did not ameliorate skin inflammation." (PMID 30937919, 2019).
colorectal cancer (59 papers, 2013 to 2025). A primary or metastatic malignant neoplasm that affects the colon or rectum. "The overexpression of IL-17 is linked to a poor prognosis in colorectal cancer, whereas the production of IL-22 is associated with a favorable clinical outcome." (PMID 39100676, 2024). "Interleukin 22 (IL-22) has been associated with resistance against chemotherapeutic drugs in patients with colorectal cancer and tumorigenesis in CRC mouse models." (PMID 37511431, 2023). "In human colorectal cancer, the infiltration of Th22 cells is associated with a good prognosis, although tumor-promoting Th17 cells can produce IL-22." (PMID 37511431, 2023). "While ILC3-derived IL-22 protects the intestinal epithelium against genotoxic stress, risk-associated single nucleotide polymorphisms have been identified within Il22 and the IL-23 signaling pathways as a driver of colorectal cancer in patients." (PMID 35359972, 2022). "For instance, both IL-17A and IL-22 have been associated with human colorectal cancer, and the increase in IL-17-producing cells has been proven to be an independent prognostic marker in human colorectal cancer." (PMID 35203436, 2022). "For instance, ILC-derived IL-22 seems to protect against genotoxic stress in the colon, whereas IL-22 derived from Th17 cells has been shown to play a pathogenic role in colorectal cancer." (PMID 33003458, 2020). "IL-10 and IL-22 are tightly associated with the prevention of mucosal inflammation and have a variety of functions in colorectal cancer development." (PMID 32670290, 2020). "In 2010, a significant association between IL-22 polymorphism (rs1179251) and colorectal cancer had been reported." (PMID 31749919, 2019). "IL-17+IL-22+ ILCs accumulate in colorectal cancer occurring in Helicobacter hepaticus associated colorectal cancer." (PMID 31024537, 2019). "Recent data have particularly implicated the cytokine Interleukin-22 (IL-22) in colorectal cancers (CRCs)." (PMID 31770366, 2019). "In another study, IL-22 produced by ILC3s promoted bacteria-induced colorectal cancer (CRC) in genetically susceptible 129SvEv.RAG−/− mice when infected with H.hepaticus and treated with the carcinogen azoxymethane (AOM)." (PMID 29587679, 2018). "Other studies showed that high expression of RORγt, which is essential for IL-22 production, and IL-17A, which is commonly found in association with IL-22, indicates poor prognosis in patients with colorectal cancer." (PMID 28492497, 2017). "Clinical data show an association between high serum IL-22 levels and resistance to chemotherapy in patients with colorectal cancer, an observation which was further confirmed in vitro." (PMID 28492497, 2017). "Moreover, levels of IL-22 are positively associated with depression, and inhibiting IL-22 expression improves depressive behavior in mice models of colorectal cancer comorbid with depression." (PMID 38218856, 2024). "A direct association has been reported between stagings of colorectal cancer with IL-22." (PMID 33042126, 2020). "Turicibacter, which is enriched in murine colorectal cancer, promotes pro-inflammatory effects, while IL-22 treatment, which boosts anti-inflammatory responses, significantly depletes Turicibacter, suggesting its involvement in inflammation." (PMID 40861440, 2025). "In colorectal cancer, IL-22-producing infiltrating CD4+ and CD8+ T-cells were correlated with a better clinical outcome and increased infiltration of neutrophils, which in turn enhanced anti-tumor T-cell responses." (PMID 39372944, 2024). "Blocking Dectin-1 can prevent colorectal cancer by inhibiting prostaglandin E2 production and enhancing the expression of interleukin-22 (IL-22)-binding proteins in myeloid-derived suppressor cells." (PMID 39100676, 2024). "In colorectal cancer, IL-22 enhances autocrine expression of IL-8 in tumor cells via STAT3 activation, assisting tumor cells survive from FOLFOX chemotherapy." (PMID 38596684, 2024).
colorectal cancer (continued). "Interleukin 22 binding protein (IL-22BP), a natural antagonist of the cytokine interleukin 22 (IL-22) has been shown to control the progression of colorectal cancer (CRC)." (PMID 37324022, 2023). "One factor that has been identified to play a crucial role in the progression of colorectal cancer is IL-22." (PMID 37324022, 2023). "The dual action of IL-22 has already been proven in colorectal cancers, where IL-22 increases inflammation during the acute phase." (PMID 37894302, 2023). "It has been found that IL22-producing CD4+ T cells promote colorectal cancer stemness which enhance tumorigenesis." (PMID 35874683, 2022). "IL-22 producing T cells in colorectal cancer enhance T cell function by recruiting neutrophils, thereby enhancing immune response." (PMID 33816497, 2021). "IL-10RB is overexpressed in colorectal cancer and through binding of IL-22 contributes to colorectal carcinogenesis." (PMID 33075095, 2020). "An increase of systemic IL-22+ and IL-17+ cells in the progression of gastric carcinoma as well as in colorectal cancer has been reported." (PMID 32298379, 2020). "IL-22 administration results in the acquisition of chemoresistance in human colorectal cancer cell lines." (PMID 33042126, 2020). "The authors also showed that CCR6+ ILC3s are the major source of IL-22 in Hh+ (Helicobacter hepaticus) driven colorectal cancer, a model in which IL-22 is essential for cancer promotion." (PMID 31024531, 2019). "have reported that T cell-derived IL-22 also promoted colorectal cancer stemness via STAT3-DOT1L axis." (PMID 31650028, 2019). "In our clinical trial, circulating inflammatory cytokines of TNF-α, IL-10, IL-12, IL-17A, IL-17C and IL-22 remained high in colorectal cancer patients even after removal of tumor." (PMID 31340751, 2019). "129SvEv.RAG−/− mice infected with H.hepaticus and treated with the carcinogen azoxymethane (AOM) develop IL-22 dependent colorectal cancer." (PMID 29587679, 2018). "It should to be noted that the expression of proinflammatory cytokines such as IL-17A, IL-6, IL-22 was dramatically increased in lesions of colorectal cancer and their high expression significantly correlated with cancer progression and poor prognosis." (PMID 28811578, 2017). "It has also been reported that ILC3-derived IL-22 promotes the proliferation of colorectal cancer cells." (PMID 28638068, 2017). "In hepatocellular carcinoma, pancreatic cancer, and colorectal cancer, IL-22 expression positively correlated with tumor growth, metastasis, and tumor stages." (PMID 27303405, 2016). "In this context, it is noteworthy that IL-22 produced by ILCs facilitates the growth of cancer cells through a STAT3-dependent mechanism in a bacteria-driven mouse model of colorectal cancer." (PMID 25061260, 2014). "For example, it has been demonstrated that IL-22 acts on colorectal cancer cells to promote the activation of transcription factor STAT3 and expression of histone H3 lysine 79 methyltransferase, consequently increasing cancer stemness and tumorigenic potential." (PMID 38098005, 2023). "IL-22 has been reported to promote stemness in colorectal cancer and Kras-mutant lung cancer." (PMID 38098005, 2023). "IL22 signaling interacts with mutant KRAS to promote poor prognosis in colorectal cancer." (PMID 35874683, 2022). "However, there are few data about the prognostic significance of interleukin-22 in human colorectal cancer which is still debated." (PMID 34296212, 2021). "IL-22 producing CD4+ T cells have been shown to enhance the stemness of colorectal cancer." (PMID 33042126, 2020). "This study shows that when APC is mutated in murine intestinal epithelial cells, they no longer respond to IL-22, a cytokine that is considered important for colorectal cancer progression; this has implications for IL-22 as a therapeutic target for cancer treatment." (PMID 31770366, 2019). "Multiple studies have also shown that IL-22 alone can promote colorectal cancer progression." (PMID 29922293, 2018).
colorectal cancer (continued). "Moreover, the overexpression of IL-22 or its receptor was correlated with tumor progression in digestive cancers, such as pancreatic, gastric and colorectal cancer." (PMID 29262587, 2017). "Additionally, in colorectal cancer and lung cancer cells, IL-22 contributes to resistance to chemotherapy by activating STAT3 and subsequently upregulating antiapoptotic genes." (PMID 27303405, 2016). "A decrease in IL22 following NPS 2143 treatment (together with the reduction in COX2 expression) could thus indicate that CaSR inhibition may indirectly be protective against colorectal cancer development." (PMID 39770982, 2024). "Here we show an increased presence of IL-17+IL-22+ cells and TGF-β1 in colorectal cancer compared to normal adjacent tissue, whereas the frequency of IL-22 single producing cells is not changed." (PMID 32451418, 2020). "The concurrent neutralization of either IL-6 and IL-22 or TNF-α and IL-17A inhibited NF-κB or STAT3 signaling, respectively, and reduced the mitogenic effects of these cytokines on human colorectal cancer cells." (PMID 29922293, 2018). "Regarding the role of IL-22 in tumour immunity, IL-22-producing CD4 T cells were discovered in malignant pleural effusion, gastric cancer, pancreatic cancer, colorectal cancer, and B-chronic lymphocytic leukaemia." (PMID 29089667, 2017). "C. albicans mediates the up-regulation of macrophage glycolytic pathway, and up-regulates the expression and secretion of IL-7, and then induces type 3 intrinsic lymphocytes (ILC3) to express high levels of IL-22 through AhR and STAT3 pathways, which aggravates the progression of colorectal cancer." (PMID 37333850, 2023). "SAA expression was promoted by IL-22 in normal mouse cells, by lipopolysaccharide (LPS) in mouse colorectal cancer cell lines, as well as by a combination of IL-1ß, IL-6, and tumor necrosis factor-α (TNF-α) in human colorectal cancer cell lines." (PMID 35303008, 2022). "In another study, anti-Il-22 but not anti-Il-17 treatment significantly reduced the incidence rate of colorectal cancer in Hh+AOM-treated 129Rag2−/− mice." (PMID 33255175, 2020). "Since chronic inflammation is a potent driving force for the development of human colorectal cancer (CRC), the contributions of TH9/IL-9, TH17/IL-17, and TH22/IL-22 in the pathogenesis of CRC have recently become an increasingly popular area of scientific investigation." (PMID 31637216, 2019). "IL-22 binds to the receptor complex comprising IL-10R2 and IL-22R1 to activate the transcription factor STAT-3 and promote tumor progression in several cancer types, including colorectal cancer and BC." (PMID 29262587, 2017). "Notably, IL-22-producing CD4+ T cells have been shown to enhance colorectal cancer cell stemness, with colonic dendritic cells contributing to local IL-22 production independent of their maturation state." (PMID 40944286, 2025). "Importantly, IL22+ T cells and non-T cells are present in human colorectal cancer, and IL22 gene expression is increased in cancer tissue relative to matched adjacent normal tissue in these patients." (PMID 29081776, 2017). "Similarly, while ILC3-derived IL-22 is critical for supporting homeostatic intestinal barrier function, epithelial cell repair and regeneration, chronic overproduction of IL-22 by ILC3 may promote colorectal cancers." (PMID 29085366, 2017). "Here the authors show that a population of IL-17+IL-22+, but not single IL-22+, CD4+ T cells are induced by TGF-β, enriched in patients with colorectal cancer (CRC) and drive CRC progression in mice." (PMID 32451418, 2020).
Crohn disease (57 papers, 2010 to 2025). A gastrointestinal disorder characterized by chronic inflammation involving all layers of the intestinal wall, noncaseating granulomas affecting the intestinal wall and regional lymph nodes, and transmural fibrosis. "The increase in IL17 and IL22 in Crohn’s disease is associated with disrupted epithelial regeneration and limits the expansion of intestinal stem cells (ISCs)." (PMID 37189778, 2023). "Colonic ILC3s from ulcerative colitis and Crohn’s disease patients produce higher IL-22 levels than healthy control subjects, and this excessive IL-22 can cause GI inflammation." (PMID 36637514, 2023). "Having determined that psychological stress impairs IL-22-driven protective mucosal immunity against Crohn’s disease-associated pathobionts, we reasoned that reconstituting IL-22 during stress should correct this defect and restore mucosal defenses." (PMID 34795263, 2021). "We conclude that psychological stress impairs IL-22-driven protective immunity in the gut, which creates a favorable niche for the expansion of pathobionts that have been implicated in Crohn’s disease." (PMID 34795263, 2021). "Activation of AHR can augment the production of IL‐22, an inflammatory cytokine, causing cutaneous inflammation, PCOS, or Crohn's disease." (PMID 38468402, 2024). "In another study, IL-22 administration induced the intestinal epithelial cells to increase tight junction protein expression in Crohn's disease patients; also, anti-TNF therapy increased IL-22 production in CD4+ T cells." (PMID 35224555, 2022). "Additional evidence points to increased expression of IL-22 in patients with Crohn’s disease through a Th1- mediated STAT1 and STAT3 activation, further implicating its role in innate immune activation." (PMID 35628427, 2022). "In order to observe the effects of moxibustion and acupuncture on the expression of IL-17A and IL-22 in Crohn's disease rats, Liu established the Crohn's disease model with 2,4,6-trinitrobenzene sulfonic acid (TNBS)." (PMID 35075366, 2022). "Additional evidence suggests that individuals who had intestinal inflammation due to Crohn’s disease had a shift from IL-22 producing ILC3 to CD127 + IFN-γ producing ILC1 under the influence of IL-2 and IL-12." (PMID 34445953, 2021). "Inflamed mucosal tissues and inflammatory diseases of the gut [inflammatory bowel diseases (IBDs) and Crohn’s disease (CD)] were associated with increased frequency of IFN-γ/IL-17A-producing ILCs and reduced frequency of IL-22-producing ILCs." (PMID 34804991, 2021). "Elevated IL-22 levels have been detected in patients with Crohn's disease, as well as increased IL-22 and IL-22Rα expressions in colon biopsy samples from UC patients." (PMID 32670290, 2020). "In the colon of patients with active colonic Crohn’s disease (CD), there was enrichment of IL22-responsive transcriptional modules and ER stress response modules." (PMID 31792136, 2020). "Inflammation associated with Crohn’s disease (CD) is believed to be driven by Th1 cells, producing IFN-ɣ and IL 2, and Th17 cells producing IL-17 and IL-22." (PMID 30028859, 2018). "The systemic IL-22 levels were elevated in Crohn’s disease patients (<24 pg/mL) in comparison with healthy participants and systemic IL-22 should derive from the sites where activated T cells were present." (PMID 27424033, 2016). "Recent studies have demonstrated that patients with IBD, specifically Crohn's disease or ulcerative colitis have increased IL-22 expression in the colonic tissue." (PMID 26793707, 2015). "Highly elevated serum levels and a potential systemic role for IL-22 have been demonstrated to correlate with disease severity in patients with Crohn’s disease (CD)." (PMID 23379788, 2013). "Elevated levels of IL-22 have been found in the mucosa of Crohn’s disease, but its role in CD is yet unclear." (PMID 23145841, 2012).